PDIA3 (protein disulfide isomerase family A member 3)
Diseases named in the same sentence as PDIA3 in open-access papers (continued):
Sharing a sentence is not in itself a finding about the gene and the disease.
schizophrenia (2 papers, 2014 to 2025). A major psychotic disorder characterized by abnormalities in the perception or expression of reality. "Specifically, AGER, PDIA3 and NAGA appeared to have an effect on schizophrenia." (PMID 40281223, 2025).
steatosis (2 papers, 2012 to 2015). Increased lipid within the cytoplasm of cells. "Our results suggested that ER chaperone PDIA3 plays a pivotal role in FFA-induced hepatocyte steatosis and apoptosis." (PMID 26214517, 2015). "We have observed increased steatosis and suppressed apoptosis after chronic ethanol binge with concomitant increases in the levels of PDIA3 acidic isoforms." (PMID 22545783, 2012).
aortic valve stenosis (1 paper, 2019). Aortic valve stenosis (AVS) is a condition characterized by narrowing of the heart's aortic valve opening. "We detected an upregulation of complement 9 (C9), serum amyloid P-component (APCS) and transgelin as well as downregulation of heat shock protein (HSP90), protein disulfide isomerase A3 (PDIA3), annexin A2 (ANXA2) and galectin-1 in patients with aortic valve stenosis." (PMID 31856737, 2019).
atherosclerosis (1 paper, 2024). A disease characterized by the build-up of fatty material and calcium deposition in the arterial wall resulting in partial or complete occlusion of the arterial lumen. "A key finding based on analysis of protein interactions in this network is that PDIA3 interactome plays a key role in atherosclerosis." (PMID 38984353, 2024). "The involvement of the PDIA3 interactome in atherosclerosis was further assessed by identifying potential network–network interactions regulated by proteins in swarm cluster 3,620–3,633 (CCSV0.99) containing PDIA3 and proteins expressed in all tissues." (PMID 38984353, 2024).
autoimmune hepatitis (1 paper, 2024). Hepatitis caused by autoantibodies. "Increased humoral responses to PDIA3 were also observed in patients across a diverse array of chronic inflammatory liver conditions, such as autoimmune hepatitis, primary biliary cholangitis, and T2D, further supporting PDIA3 as an important liver-derived autoantigen during liver inflammation." (PMID 39616399, 2024).
Azoospermia (1 paper, 2024). Absence of any measurable level of sperm,whereby spermatozoa cannot be observed even after centrifugation of the semen pellet. "This preliminary investigation involved measuring and comparing the serum protein levels of PDIA1, PDIA3, MANF, GRP78, CLU, CRT, and CNX in patients diagnosed with idiopathic nonobstructive azoospermia and noninfertile male controls." (PMID 39237030, 2024).
brucellosis (1 paper, 2025). Brucellosis is a bacterial infection that spreads from animals to people via unpasteurized dairy products or by exposure to contaminated animal products or infected animals. "The abnormal levels of CDK1, MAPK11, PDIA3, and immune cells in brucellosis may be involved in the disease’s pathogenic mechanisms." (PMID 40996975, 2025). "Importantly, through the analysis with GBM and Random Forest models, CDK1, MAPK11, and PDIA3 were further identified as potential diagnostic marker genes for brucellosis." (PMID 40996975, 2025). "RT-qPCR validation confirmed that the mRNA levels of CDK1, MAPK11, and PDIA3 were significantly elevated in brucellosis patients compared to the control group." (PMID 40996975, 2025). "In the GSE69597 dataset, the expression levels of CDK1, MAPK11, and PDIA3 were significantly higher in patients with brucellosis compared to the control group." (PMID 40996975, 2025). "Similarly, Western blot experiments revealed that the protein expression levels of CDK1, MAPK11, and PDIA3 were significantly higher in patients with brucellosis than in the control group." (PMID 40996975, 2025).
cholelithiasis (1 paper, 2012). The presence of crystallized deposits forming in the gallbladder or biliary tree, primarily composed of cholesterol, bilirubin, and bile. "PDIA3 and HSPD1 could be detected in several cholelithiasis patients; however, the average expression levels of PDIA3 and HSPD1 in crude bile from CC patients was significantly higher." (PMID 23118872, 2012).
Cognitive impairment (1 paper, 2021). Abnormal cognition is characterized by deficits in thinking, reasoning, or remembering. "PDIA3 provided significant improvements in cognitive impairments and contusion volume induced by TBI through attenuating oxidative stress." (PMID 33640879, 2021).
colorectal tumors (1 paper, 2024). "Immunohistochemical evaluations disclosed conspicuously elevated levels of PDIA3 in colorectal neoplasms in comparison to healthy colonic tissues—a finding substantiated by Western blot analyses, which indicated pronounced PDIA3 expression in tumor samples." (PMID 38761176, 2024). "Utilizing the TIMER2.0 database, overexpression of PDIA3 in colorectal tumors was initially identified, and further confirmed through GEO database analysis, establishing a strong correlation between PDIA3, STAT3, and CD274." (PMID 38761176, 2024). "Comparative analysis of colorectal neoplasms and normal colon samples unveiled heightened levels of PDIA3 markers which, when overexpressed in SW480 cells, escalated tumorigenicity and oncogenic behaviors, with a noted decrease upon PD-1 monoclonal antibody intervention." (PMID 38761176, 2024).
dementia (1 paper, 2020). Loss of intellectual abilities interfering with an individual's social and occupational functions. "While there is no direct data on the participation of Coro1a in the pathogenesis of dementias, Pdia3 and Snca are known to be involved in the molecular mechanisms of AD." (PMID 32994510, 2020).
demyelination (1 paper, 2024). "Additionally, we explored the potential protective effects of CRYM and PDIA3 against cuprizone-induced demyelination by synthesizing cell-permeable Tat peptide-fusion proteins (Tat-CRYM and Tat-PDIA3) to facilitate their crossing through the blood–brain barrier." (PMID 39164609, 2024).
developmental delay (1 paper, 2025). "Recently, we have reported a loss-of-function mutation in protein disulfide isomerase A3 (PDIA3) causing severe ID accompanied by developmental delay with no gross brain abnormalities." (PMID 40719631, 2025).
diabetic nephropathy (1 paper, 2020). "For example, ERp57 (also known as PDIA3), is secreted by ER stressed cells involved in TGF-β mediated fibrogenesis, and can be detected in urines of patients with diabetic nephropathy with ongoing fibrosis." (PMID 32303684, 2020).
endometrioid endometrial adenocarcinoma (1 paper, 2023). "Among different tissue types, the expression of PDIA3 in endometrioid endometrial adenocarcinoma (EEA) was higher than that in mixed serous and endometrioid (MSAE) (P = 0.014) and serous endometrial adenocarcinoma (SEA) (P = 0.0066)." (PMID 37909009, 2023). "Moreover, PDIA3 expression in endometrioid endometrial adenocarcinoma was higher than in mixed serous and endometrioid and serous endometrial adenocarcinoma (P = 0.0455)." (PMID 37909009, 2023).
Epstein-Barr virus infection (1 paper, 2021). An infection that is caused by Epstein-Barr virus. "One was the Epstein-Barr virus infection pathway (q-value=0.025), represented by four upregulated genes (CDKN1A, NFKB2, RELB, and PDIA3) and two downregulated genes (BID and HLA-A)." (PMID 33785040, 2021).
hilar cholangiocarcinoma (1 paper, 2012). A cholangiocarcinoma that arises from the junction, or adjacent to the junction, of the right and left hepatic ducts. "Intense PGAM-1, HSPD1, PDIA3 and SSP411 cytoplasmic immunoreactivity was observed in both hilar cholangiocarcinoma and intrahepatic cholangiocarcinoma." (PMID 23118872, 2012).
Huntington disease (1 paper, 2021). Huntington disease (HD) is a rare neurodegenerative disorder of the central nervous system characterized by unwanted choreatic movements, behavioral and psychiatric disturbances and dementia. "In humans, PDIA3 is ubiquitously expressed and has been implicated in pathology such as cancer progression, Huntington’s disease, amyotrophic lateral sclerosis, and traumatic brain injury." (PMID 34922569, 2021). "A general protein disulfide isomerase inhibitor can protect against reductions in ATP levels in an in vitro Huntington disease model, supporting the notion that PDIA3 might inhibit mitochondrial bioenergetic function." (PMID 34922569, 2021).
Hyperglycemia (1 paper, 2025). An increased concentration of glucose in the blood. "Conversely, Pdia3 levels in the PFC were significantly lower in db/db mice compared with control mice, suggesting that chronic hyperglycemia and inflammation may affect non-genomic vitamin D signaling, potentially disrupting calcium regulation and protein homeostasis." (PMID 41228412, 2025).
intestinal infection (1 paper, 2015). "Nevertheless, in addition to the ER, PDIA3 is present in many other subcellular locations, which makes it difficult to predict the effects of its down-regulation over the course of the intestinal infection." (PMID 26390031, 2015).
irritable bowel syndrome (1 paper, 2016). Irritable bowel syndrome (IBS) is a chronic functional condition of the lower gastrointestinal (GI) tract characterized by abdominal pain or discomfort and disordered bowel habit (diarrhea, constipation, or fluctuation between the two). "This study investigated the mechanism of protein disulfide-isomerase A3 (PDIA3)-induced visceral hypersensitivity in irritable bowel syndrome (IBS)." (PMID 27896022, 2016).
keloid (1 paper, 2022). An irregularly shaped, elevated mark on the skin caused by deposits of excessive amounts of collagen during wound healing. "In our research, we detected upregulated BiP and PDI, which help to correct the folding of proteins, including P4HB, PDIA3, and PDIA6 in keloids." (PMID 35435317, 2022).
lymphoma (1 paper, 2022). A malignant (clonal) proliferation of B- lymphocytes or T- lymphocytes which involves the lymph nodes, bone marrow and/or extranodal sites. "For example, the upregulated expression of PDIA1 (also known as PDI) and PDIA3 (ERp57) have been reported in the cancers of brain, lymphoma, kidney, ovarian, prostate, lung, and colon and have been considered as diagnostic biomarkers and therapeutic targets for cancer treatment and chemoprevention." (PMID 35860571, 2022).
major depression (1 paper, 2014). "Data regarding the relationship between PDIA3 and major depression are scarce." (PMID 24383611, 2014). "The levels of protein disulfide-isomerase A3 (PDIA3) and F-actin-capping protein subunit beta (CAPZB) were higher in patients with major depression than in healthy controls." (PMID 24383611, 2014). "The most interesting finding in this study was higher PDIA3 expression and lower FGB, GPX-1, and RARB expression in patients with major depression than in healthy controls." (PMID 24383611, 2014). "Therefore, PDIA3, SPR, and the other proteins identified might provide a link to the possible psychopathology of major depression." (PMID 24383611, 2014).
Miscarriage (1 paper, 2022). A pregnancy that ends at a stage in which the fetus is incapable of surviving on its own, defined as the spontaneous loss of a fetus before the 22th week of pregnancy. "There was an additive interaction between serum anti-ENO1-P6 and anti-PDIA3 total IgGs on the development of miscarriage (RERI = 23.6, AP = 0.79, SI = 5.37)." (PMID 35707546, 2022). "It was further investigated whether there was any interaction between anti-ENO1-P6 and anti-PDIA3 total IgG expressions in TAI-related miscarriage." (PMID 35707546, 2022). "However, there was an additive interaction between anti-ENO1-P6 and anti-PDIA3 total IgGs on the development of miscarriage (RERI = 23.6, 95% CI = −18.1, 65.3; AP = 0.79, 95% CI = 0.47, 1.11; SI = 5.37, 95% CI = 1.03, 27.87)." (PMID 35707546, 2022). "The results showed that there was a positive correlation between anti-ENO1-P6 and anti-PDIA3 total IgG levels in the TAI-miscarriage group (P = 0.027; rs = 0.368), but not in the TAI-non-miscarriage group (P = 0.317; rs = 0.125)." (PMID 35707546, 2022).
myeloma (1 paper, 2022). "Our findings show that EV-derived proteins (PDIA3, BTN1A1, APRIL) and complement-associated proteins could be further explored in myeloma, as biomarkers across disease natural history and as potential new drug targets that could be monitored by PB sampling." (PMID 35800053, 2022). "We report a set of PB EV-proteins (PDIA3, C4BPA, BTN1A1, and TNFSF13) with a new biomarker potential for myeloma patient outcomes." (PMID 35800053, 2022).
myocarditis (1 paper, 2011). Myocarditis is a condition that is characterized by inflammation of the heart muscle (myocardium). "Strikingly, of the 39 up-regulated proteins identified in this experiment, UPR target genes, such as GRP78, GRP94, Hspb1, Calr, and Pdia3, were also increased in the acute phase of CVB3-infected myocarditis mouse heart tissues." (PMID 22014063, 2011).
Neurodegeneration (1 paper, 2022). Progressive loss of neural cells and tissue. "At the same time, it was hypothesized that ERp57/PDIA3 involvement in neurodegeneration diseases is related to its role as vitamin D3 receptor." (PMID 35109791, 2022).
preeclampsia (1 paper, 2012). Preeclampsia is a hypertensive disorder of pregnancy that is characterized by new-onset hypertension with proteinuria presenting after 20 weeks of gestation, and depending on mild or severe forms may initially present with severe headache, visual disturbances, and hyperreflexia. "However, there are not articles of PDIA3, TBK1 or LYN related with preeclampsia." (PMID 22873350, 2012).
protein misfolding diseases (1 paper, 2016). "The proteins encoded by APLP2, PTN, DCN, GPNMB, P4HB, and PDIA3, have been associated with either protein misfolding diseases or TSEs but their specific role in prion protein degradation has not been described." (PMID 26807844, 2016).
Stroke (1 paper, 2021). Sudden impairment of blood flow to a part of the brain due to occlusion or rupture of an artery to the brain. "This presents an important step forward in understanding PDIA3 functions related to STAT3 signaling and new avenues for therapeutic intervention for diseases such as stroke." (PMID 34922569, 2021).
tauopathies (1 paper, 2023). "Thus, the inhibition of PDIA3 may be an effective strategy for regulating tauopathies and modulating AD progression." (PMID 36769334, 2023). "The inhibition/suppression of PDIA3, leading to conditional stimulations of the PERK signaling pathway, showed beneficial effects on mice with tauopathies." (PMID 36769334, 2023).
thyroid (1 paper, 2022). "It is also reported that the expression of PDIA3 autoantibody increased the risk of miscarriage in thyroid women with thyroid autoimmunity; this suggested that PDIA3 antibody may result in associated adverse complications." (PMID 35401558, 2022).
tick-borne diseases (1 paper, 2022). "4-HNE, generated during tick-borne diseases, also binds to other metabolically important proteins, including GSH transferase, ANGPT4, clathrin, PDIA3, actinin-4, and PRDX5." (PMID 35457192, 2022).
Type 2 Diabetes (1 paper, 2022). "Recently, we demonstrated that in Type 2 Diabetes (T2D), the chronic inflammatory environment increased the MHC II presentation of peptides derived from stress-associated proteins by local dendritic cells, including protein disulfate isomerase-3 (PDIA3)." (PMID 36405763, 2022).
cancer (108 papers, 2007 to 2025). A tumor composed of atypical neoplastic, often pleomorphic cells that invade other tissues. "Several studies highlight that PDIA3 expression is upregulated in various cancers and tightly associated with the occurrence, development, invasion, and metastasis of tumor cells." (PMID 39408858, 2024). "Within the PDI family, PDIA3 (also known as ERp57) is of particular interest for its emerging association with progression of certain cancers." (PMID 36374169, 2023). "Given the importance of the PI3K/AKT signaling pathway in cancer, we studied the association between PDIA3 and the AKT pathway in OSCC." (PMID 38213579, 2023). "Gene Set Enrichment Analysis (GSEA) was applied to search the associated cancer hallmarks with PDIA3 expression." (PMID 35401558, 2022). "Results from OS, DSS, DFI, and PFI analyses were highly consistent, showing that PDIA3 is significantly associated with the prognosis of cancer patients, and PDIA3 is a risk factor for a large proportion of cancers." (PMID 35401558, 2022). "In conclusion, PDIA3 is one of the most reported PDI members in cancer progression and associated with immune evasion by T-cell killing." (PMID 35401558, 2022). "DFI and PFI outcomes were also examined to fully demonstrate that PDIA3 is a risk factor in most cancer types and significantly related to the prognosis of cancer patients." (PMID 35401558, 2022). "The close association between PDIA3 and the occurrence and development of cancer has been corroborated by numerous studies." (PMID 35401558, 2022). "PDIA3 is highly expressed in most cancers, and its expression is associated with overall low cell survival, metastasis, and invasiveness." (PMID 35957802, 2022). "PDIA3 expression is elevated in almost 70% of cancers and its expression has been linked with overall low cell invasiveness, survival and metastasis." (PMID 35860021, 2022). "The heatmap showing the prognosis analysis of PDIA3 in pan-cancer indicated that PDIA3 is highly associated with the prognosis of most cancers except CHOL, PCPG, SKCM, THYM, UCEC, and UCS." (PMID 35401558, 2022). "Several studies associate changed expression of PDIA3 with multiple pathologies including cancer and neurodegenerative disease." (PMID 33761087, 2021). "In this work, a subset of cancer-related variants known to be in PDIA3 (ERp57) and TAPBP (tapasin) genes were collected from cBioPortal, to access data from the cancer genome atlas (TCGA) and other genomic studies." (PMID 32244998, 2020). "Several studies have linked PDIA3 to different types of cancer, including breast, ovarian, and colon cancers." (PMID 31886273, 2019). "Expression of PDIA3 is increased in more than 70% of cancers and its expression has been associated with cell invasiveness, metastasis, and low overall survival." (PMID 28044092, 2016). "The expression level of PDIA3 in cancer cells is linked to tumor progression and prognosis of some human tumors." (PMID 23782473, 2013). "Abnormal expression or function of PDIA3 has been found to be associated with certain diseases, such as inflammatory response, neurodegenerative diseases, and cancer." (PMID 40028181, 2025). "PDIA3 is implicated in numerous pathologies such as cancer, inflammation, and neurodegeneration." (PMID 39408858, 2024). "PDIA3 has been also linked to various diseases from neurodegenerative to cancer." (PMID 37960182, 2023). "Together, these currently available studies indicate that PDIA3 is associated with a shorter survival time in cancer patients and may be used as a biomarker for poor prognosis in cancer patients." (PMID 38213579, 2023). "In conclusion, these results indicated that a higher PDIA3 expression is associated with the immune-activation status of cancers and might provide some clues for further investigation of the functions and roles of PDIA3 in cancer initiation and progression." (PMID 35401558, 2022).